SIX6 (SIX homeobox 6)
Description:
May be involved in eye development.
Synonyms: OPTX2; SIX9; MCOPCT2; ODRMD
Tractability: PROTAC: ubiquitination databases record sites on it.
Gene: Protein-coding gene on chromosome 14 (60,509,146 to 60,512,850, forward strand). Ensembl gene ENSG00000184302.
Subcellular location: Nucleus
Subcellular location (Human Protein Atlas): Nucleoplasm
Gene Ontology:
Molecular function: RNA polymerase II cis-regulatory region sequence-specific DNA binding; sequence-specific double-stranded DNA binding; DNA-binding transcription factor activity, RNA polymerase II-specific; DNA binding
Biological process: animal organ morphogenesis; eye development; regulation of transcription by RNA polymerase II; visual perception
Cellular component: chromatin; nucleus; transcription regulator complex
Genetic constraint (gnomAD): Loss-of-function variants: 14 observed, 23.77 expected, observed/expected ratio (o/e) 0.59, 90% interval 0.39 to 0.92. The upper end of that interval is the gene's LOEUF score, 0.92, which puts it in group 3 of 6, group 1 being the genes least tolerant of losing a copy. Missense variants: 307 observed, 338.35 expected, observed/expected ratio (o/e) 0.91, 90% interval 0.83 to 1. Synonymous variants: 128 observed, 156.64 expected, observed/expected ratio (o/e) 0.82, 90% interval 0.71 to 0.95.
Homologues: Orthologues: chimpanzee SIX6 (100% identical), macaque SIX6 (99% identical), rabbit SIX6 (99% identical), dog SIX6 (98% identical), mouse Six6 (98% identical), rat Six6 (98% identical), guinea pig SIX6 (98% identical), pig SIX6 (98% identical), tropical clawed frog six6 (93% identical), zebrafish six6a (91% identical), zebrafish six6b (91% identical), Drosophila melanogaster Optix (71% identical), and 1 more. Paralogues in human: SIX3 (82% identical), SIX1 (54% identical), SIX2 (54% identical), SIX4 (50% identical), SIX5 (49% identical), ANHX (27% identical).
Diseases named in the same sentence as SIX6 in open-access papers:
SIX6 is named in the same sentence as 43 diseases in open-access papers, as found by Europe PMC text mining. Sharing a sentence is not in itself a finding about the gene and the disease. The quoted sentences say what the papers report.
glaucoma (27 papers, 2012 to 2025). Increased pressure in the eyeball due to obstruction of the outflow of aqueous humor. "Epidemiological data associate glaucoma prevalence with aging, while the glaucoma-risk gene SIX6, overexpressed in glaucomatous Müller cells and astrocytes, drives senescence via p16INK4 upregulation." (PMID 41409280, 2025). "The rs944801, an intron variant within CDKN2B-AS1, and rs2093210, an intron variant within SIX6, are known to be associated with vertical cup-disc ratio, an important optic nerve head parameter that is often used to define or diagnose glaucoma." (PMID 39482785, 2024). "Other frequently observed genes are related to eye diseases (PDE6G has been linked to Retinitis Pigmentosa, and SIX6 to glaucoma, myopia, and retinal degeneration) or vascular processes (FLT1 linked to hypertension and heart disease)." (PMID 39505872, 2024). "The SIX homeobox 6 (SIX6) gene, a senescence-related gene, is also a risk gene for glaucoma, including NTG." (PMID 36769067, 2023). "In the present context, it is significant that genes known to be associated with glaucoma were found to be predominantly expressed in ganglion cells, sometimes selectively—e.g., SIX6 in midgets." (PMID 34093409, 2021). "Genes with type-specific RGC expression patterns included the glaucoma-associated genes SIX6, which was enriched in midget ganglion cells; CAV2 and POU6F2 enriched in ON parasol RGCs and AFAP1, enriched in peripheral ON parasol RGCs." (PMID 32555229, 2020). "Homozygosity of glaucoma-risk alleles in SIX6 in a glaucoma mouse model led to RGC senescence through p16INK4a overexpression." (PMID 33303874, 2020). "We observed that rs10483727—the only SIX1/SIX6 SNP previously associated with glaucoma susceptibility by GWAS—was in close linkage disequilibrium (LD) with rs33912345 (R-sq = 0.99 in the JPT 1000 genomes dataset)." (PMID 28663559, 2017). "Of these, only the CDKN2BAS and SIX1/SIX6 regions were significantly associated with glaucoma in the meta-analysis, although several other previously identified gene regions demonstrated suggestive associations including SALL1, LRP1B and SIRPA." (PMID 22570617, 2012). "Additionally, we detected the variant p.T212M in the SIX6 gene in a patient with a moderate glaucoma." (PMID 38241218, 2024). "Modified animal models with this variant have been found to have a smaller eye size, hypothesizing that the presence of hypomorphic alleles in SIX6 could reduce the number of retinal ganglion cells and increase the risk of glaucoma." (PMID 38241218, 2024). "Interestingly, previous works have shown that the rs146737847 (Glu129Lys) adversely affects the SIX6 gene function and is also associated with primary open-angle glaucoma potentially through its known effect over the vertical cup-disc ratio." (PMID 36137074, 2022). "Additionally, Notch1 expression is dependent upon both Six3 and Six6 in retinal development and expression of human SIX6 glaucoma risk alleles in Xenopus embryos downregulated the Notch pathway." (PMID 34490256, 2021). "SIX1/SIX6 polymorphism has been shown to be associated with glaucoma." (PMID 32719476, 2020). "Furthermore, the fine-sectored cpRNFLT analysis indicated that SIX1/SIX6 polymorphisms would affect cpRNFL thinning at 281.3–303.8°, which corresponds to parafoveal scotoma in a visual field test of glaucoma patients." (PMID 28663559, 2017). "In this paper, we test specific sequence variants in SIX6 that are found in glaucoma patients." (PMID 24875647, 2014). "Those rare variants are located in CYP1B1, SIX6, CARD10, MFN1, OPTC, OPTN, and WDR36 glaucoma-related genes." (PMID 38241218, 2024). "A previous study has demonstrated that SIX6 induces the expression of the senescence gene p16INK4 and mediates the pathogenesis of glaucoma." (PMID 36769067, 2023). "Homeobox genes such as SIX6/SIX1, LMX1b and MEIS, which play prominent roles in development, have been shown to be associated with glaucoma." (PMID 36148008, 2022).
glaucoma (continued). "SIX6 has been connected with various eye malformations including anophthalmia and microphthalmia, primary open angle glaucoma (POAG), and optic disk anomalies and macular atrophy." (PMID 34490256, 2021). "Here we have identified a set of genes in POAG-associated loci whose expression is altered in the RGCs (e.g., Ank, Cadm2, and Six6) and the optic nerve head (e.g., Cadm2 and Cdkn2b) in a mouse model of glaucoma." (PMID 29891935, 2018). "Our results, in combination with previous SIX6 work, lead us to hypothesize that SIX6 risk variants disrupt the development of the neural retina, leading to a reduced number of retinal ganglion cells, thereby increasing the risk of glaucoma-associated vision loss." (PMID 24875647, 2014). "For example, SIX6 risk variation, silent information regulator T (SIRT) 1, and Forkhead Box O (FOXO) transcription factor 1 and 3a ( FOXOs 1 –3a), which is the key to the pathogenesis of glaucoma or optic nerve degeneration." (PMID 35366826, 2022). "The SIX6 locus is the only locus clearly associated with GCIPL or RNFL and glaucoma." (PMID 33979322, 2021). "It has been demonstrated that non-glaucomatous subjects with the SIX6 missense variant exhibited reduced RNFL thickness in regions mainly affected by glaucoma." (PMID 32545285, 2020). "The significance of the SIX1/SIX6 locus in glaucoma has been previously discovered for VCDR and POAG, whereas the subsequent research confirmed a direct correlation between polymorphisms in this region and glaucoma onset." (PMID 32545285, 2020). "Several polymorphisms in the genes SIX6 and ATOH7 were identified that are responsible for thinner retinal nerve fiber layer due to fewer RGCs, suggesting that humans with fewer RGCs are at increased risk of developing glaucoma." (PMID 29370175, 2018). "Because VFD in this region typically results from early-stage glaucoma, SIX1/SIX6 could be associated with initial changes in GON; however, optic fissure closures—known as colobomas—also present in this area." (PMID 28663559, 2017). "Despite the known association between SIX1/SIX6 SNPs and glaucoma development, these patients were not specifically excluded from the study population since we did not perform visual field testing or slit lamp biomicroscopy required for this diagnosis." (PMID 28663559, 2017). "Two top common variants in CDKN2B-AS1 and SIX6, thought to impact optic nerve vulnerability in POAG,31–33 were significantly associated with glaucoma risk in participants ≥63 years, but the risk did not vary significantly with age (Pinteraction ≥ 0.39)." (PMID 39982391, 2025). "The finding of reduced peripapillary RFNL thickness in patients with the SIX6 risk variant, but not in those with the GAS7 variant, implies that the pathologic changes in glaucoma associated with the SIX6 variant may occur primarily in the RGCs and their axons." (PMID 29261660, 2017).
microphthalmia (7 papers, 2008 to 2024). Congenital or developmental anomaly in which the eyeballs are abnormally small. "In humans, a complete loss of SIX6 function has been reported to cause optic disc anomalies, microphthalmia or anophthalmia." (PMID 31207931, 2019). "A heterozygous SIX6:p.Thr165Ala substitution was found in a human patient with congenital bilateral asymmetric microphthalmia, cataract and nystagmus." (PMID 31207931, 2019). "Further sequence analysis of other genes associated with anophthalmia and microphthalmia such as PAX6, BCOR, OTX2, SIX6, and CHD7 is ongoing in this study cohort to determine mutation associations." (PMID 18385794, 2008). "PAX2 malformations have been associated with optic nerve coloboma, SIX6 mutations with bilateral anophthalmia and pituitary abnormalities as well as microphthalmia, CHX10 mutations with microphthalmia, and SHH mutations with human microphthalmia and coloboma." (PMID 19158959, 2009). "Overall, there is no firm evidence that mutation in SIX6 alone can cause microphthalmia, anophthalmia, or coloboma." (PMID 20057906, 2009). "Mutations in several genes have been reported in patients with microphthalmia and/or coloboma, including BMP4 (OMIM 112262), VSX2 (CHX10; OMIM 142993), CRYBA4 (OMIM 123631), OTX2 (OMIM 600037), RAX (OMIM 601881), SIX6 (OMIM 606326), and SOX2 (OMIM 184429)." (PMID 20057906, 2009).
Anophthalmia (4 papers, 2008 to 2019). Absence of the globe or eyeball. "SIX6 haploinsufficiency was suggested to be the cause of bilateral anophthalmia and pituitary anomalies." (PMID 31207931, 2019). "Interstitial deletions at 14q22.3-q23, where SIX6 is located, were found in three patients with bilateral anophthalmia, absence of the optic nerve, and chiasm and pituitary abnormalities." (PMID 20057906, 2009).
breast carcinoma (4 papers, 2015 to 2023). "SIX6 has been validated to serve as a predictor for breast cancer metastasis." (PMID 38018033, 2023). "Sineoculis homeobox homolog (SIX) family proteins, including SIX1, SIX2, SIX3, SIX4, SIX5, and SIX6, have been implicated in the initiation and progression of breast cancer, but the role of each member in breast tumor is not fully understood." (PMID 27399099, 2016). "Moreover, SIX genes are deregulated in several types of malignancies, including breast cancer and hepatocellular carcinoma (SIX1), lung cancer (SIX2), chondrosarcoma (SIX3), and acute T-cell leukemia (SIX6)." (PMID 26473286, 2015). "SIX1 and SIX6 could serve as an unfavorable factor for prognosis of luminal breast cancer patients, while SIX3 is capable of playing a protective role in prognosis of basal-like breast cancer patients." (PMID 27399099, 2016).
myopia (4 papers, 2022 to 2025). "We identify associations between population spherical equivalent and rare variants located within the protein-coding regions of the SIX6 gene, which plays an important role in eye morphogenesis and is implicated in several ocular disorders, including myopia." (PMID 36137074, 2022). "Both SIX6 and CRX have previously been implicated in myopia development, however—as discussed later—the two novel, rare missense variants identified here had much larger effects than those identified in previous GWAS investigations." (PMID 35022715, 2022).
acute T-cell leukemia (2 papers, 2015 to 2021). "Recently, SIX6 has been found to be associated with T-cell acute lymphoblastic leukemia (T-ALL), though the researchers of the study concluded that SIX6 most likely belonged to a larger regulatory gene network and increased levels of SIX6 alone were not sufficient to induce development of T-ALL." (PMID 34490256, 2021).
adenosquamous carcinoma (1 paper, 2013). A carcinoma composed of malignant glandular cells and malignant squamous cells. "The co-methylation of SIX6 and SOX1, or the co-methyaltion of SIX6, RARB and SOX1 was associated with adenosquamous carcinoma (ADC), and the co-methylation of BCL2, RARB and SIX6 was associated with smoking." (PMID 23599765, 2013).
aniridia (1 paper, 2009). Aniridia is a congenital ocular malformation characterized by the complete or partial absence of the iris. "In that study, the c.608G>A variation in SIX6 was detected in an individual with typical congenital aniridia and a previously determined PAX6 mutation (c.718C>T, p.R240X)." (PMID 20057906, 2009). "The internal control was from a girl with typical aniridia and an identified c.718C>T (p.R240X) mutation in PAX6, suggesting the c.608G>A variation in SIX6 was unlikely to play a role in her ocular phenotype." (PMID 20057906, 2009).
iris coloboma (1 paper, 2024). "Notably, this gene is involved in neural retinal development and is an acknowledged ortholog of the mammalian SIX6 gene, whose mutations are reported to cause iris coloboma." (PMID 38674426, 2024).
lung diseases (1 paper, 2013). "The methylation frequencies (29.70–64.36%) of 7 genes (MYF6, SIX6, SOX1, RARB, BCL2, PHOX2A and FOLX2) in stage I NSCLC were significantly higher compared with those in non-cancerous lung disease controls (P<0.05)." (PMID 23599765, 2013). "The methyaltion frequencies of 7 genes: MYF6, SIX6, SOX1, RARB, BCL2, PHOX2A and FOLX2 were significantly higher in stage I NSCLC than in non-cancerous lung diseases." (PMID 23599765, 2013). "In this study, among the 7 genes which demonstrated hypermethylation in stage I NSCLC compared with non-cancerous lung diseases, 5 genes (MYF6, SIX6, PHOX2A, FOLX2 and SOX1) were found for the first time to be abonormally methylated in NSCLC." (PMID 23599765, 2013). "A panel of 4 genes (MYF6, SIX6, BCL2 and RARB) was able to diagnose stage I NSCLC from non-cancerous lung diseases with a sensitivity of 93.07% and a specificity of 86.67%." (PMID 23599765, 2013). "This study showed that 7 genes (MYF6, SIX6, SOX1, RARB, BCL2, PHOX2A and FOLX2) were frequently methylated in 101 cases of patients with stage I NSCLC, while rarely methylated in 30 patients with non-cancerous lung diseases." (PMID 23599765, 2013).
lymph node metastasis (1 paper, 2016). "SIX4 and SIX6 were linked to the lymph node metastasis (LNM)." (PMID 27821176, 2016).
migraine (1 paper, 2018). "Six6 is a transcription factor for H2A histone family member Z (H2afz) that has been associated with the effects of abused substances and migraine is one of these symptoms." (PMID 30618656, 2018).
neuroblastoma (1 paper, 2019). Neuroblastoma (NB) is the most common solid, extracranial childhood tumor. "Overall, we found that downregulation of 7 genes (Crb1, Lrrc9, Rcn1, Rtl1, Shisa3, Six6, St18) and upregulation of 2 genes (C1ql3, Slc18A1), are strongly predictive of favorable neuroblastoma outcome, consistent with delayed tumor development in Th-MYCN/Casp2−/− mice." (PMID 30670683, 2019).
periodontitis (1 paper, 2022). An acute or chronic inflammatory process that affects the tissues that surround and support the teeth. "Furthermore, 12 hub genes ranked by the top 10% genes with high degree connectivity and five TFs, including SRF, CNOT4, SIX6, SRRM3, NELFA, and ONECUT3, were identified and might play crucial roles in the molecular pathogenesis of periodontitis." (PMID 35397550, 2022).
refractive error (1 paper, 2022). A defect in the focusing of light on the retina as in astigmatism, myopia, or hyperopia. "The discovery of two independently associated variants in the PRSS56, BMP4 and SIX6 genes provided additional evidence that these genes play a role in the development of refractive errors." (PMID 35022715, 2022).
squamous cell carcinoma (1 paper, 2013). A carcinoma arising from squamous epithelial cells. "The co-methylation of SIX6, RARB and SOX1 occurred less frequently in adenocarcinoma (ADC) than in squamous cell carcinoma (OR, 0.45; 95% CI, 0.25–0.76)." (PMID 23599765, 2013). "We found that the co-methylation of SIX6 and SOX1 correlated with squamous cell carcinoma (SCC), while the methylation of neither of them individually demonstrated an association with SCC, which may imply that the methylation of these two genes had a superimposed effect on the development of SCC." (PMID 23599765, 2013).
infection (7 papers, 2017 to 2025). The state of being infected such as from the introduction of a foreign agent such as serum, vaccine, antigenic substance or organism. "In comparison, FOXG_11033 is predominantly upregulated within four days post-inoculation, and the remaining four effector genes (FOXG_02829, FOXG_04863, FOXG_05755 and SIX6) were most upregulated at six days post-infection." (PMID 40985378, 2025). "Only 3 genes each in the spleen (B2m, Lst1 and Edf1) and the brain (Six6, Cd163 and Bmp10) were modulated at all three time points after V3034 infection." (PMID 28446152, 2017).
cancer (5 papers, 2013 to 2021). A tumor composed of atypical neoplastic, often pleomorphic cells that invade other tissues. "The transcriptional regulator Sox2 has been shown to be directly regulated in developmental and cancer contexts by Six1, Six2, Six3, and Six6 to further promote stem/progenitor cell phenotypes." (PMID 34490256, 2021). "The results of DNA samples from 40 cancer and 25 normal lung tissues showed a good diagnostic potential of selected RCGY sites in regulatory regions of MYF6, SIX6, RXRG, LHX1, RASSF1A and TERT genes with relatively high sensitivity (80.0 %) and specificity (88.0 %) of LC detection in tumor DNA." (PMID 31526458, 2019). "Two reports have associated hypermethylation of SIX6 with cancer types, however, expression levels of SIX6 were not addressed and it remains unclear the significance of gene methylation in these instances." (PMID 34490256, 2021). "The methylation of 4 genes, MYF6, SIX6, PHOX2A, FOLX2, has never previously been reported in any types of cancer." (PMID 23599765, 2013).
tumor (4 papers, 2015 to 2021). "During our analysis the most prominent differences connected with the location of the tumor were noted for the IRX2, PAX3, CXCL14, LHX2, SIX6, CNTN1 and SIX1 genes." (PMID 26497896, 2015).
adenocarcinoma (1 paper, 2013). A common cancer characterized by the presence of malignant glandular cells. "The co-methylation of SIX6 and SOX1 was negatively associated with adenocarcinoma (ADC) with an odds ratio (OR) of 0.24 (95% CI, 0.06–0.90)." (PMID 23599765, 2013).
SIX6 also shares sentences with these, for which no sentence is quoted: primary open-angle glaucoma (7 papers); coloboma (3); Nystagmus (2); pituitary hormone deficiencies (2); acute lymphoblastic leukemia (1); and deafness, autosomal dominant 23 (1); cerebral infarction (1); chondrosarcoma (1); congenital hypopituitarism (1); developmental eye defect (1); heart disease (1); hepatocellular carcinoma (1); Hypertension (1); lung adenocarcinoma (1); lung carcinoma (1); normal tension glaucoma (1); optic nerve coloboma (1); pancreatic cancer (1); pituitary stalk interruption syndrome (1); Retinal coloboma (1); retinal degeneration (1); retinitis pigmentosa (1); retinoblastoma (1).